ADAR (adenosine deaminase RNA specific)
Diseases named in the same sentence as ADAR in open-access papers (continued):
Sharing a sentence is not in itself a finding about the gene and the disease.
psychiatric disorder (3 papers, 2012 to 2023). A disorder characterized by behavioral and/or psychological abnormalities, often accompanied by physical symptoms. "ADAR editing, a known factor in the pathology of multiple neurodegenerative and psychiatric disorders, must be acknowledged as a potential role-player in PD pathology." (PMID 38134032, 2023).
ADAR also shares sentences with these, for which no sentence is quoted: esophageal squamous cell carcinoma (15 papers); metastatic melanoma (14); pancreatic cancer (12); non-small cell lung carcinoma (7); viral myocarditis (7); pancreatic ductal adenocarcinoma (6); triple-negative breast carcinoma (6); atherosclerosis (5); cholangiocarcinoma (5); Cognitive impairment (5); congenital heart disease (5); epilepsy (5); lymph node metastasis (5); oral squamous cell carcinoma (5); rheumatoid arthritis (5); colon cancer (4); endometrial cancer (4); esophageal cancer (4); Parkinson disease (4); pulmonary hypertension (4); thyroid tumor (4); autism (3); brain cancer (3); cognitive decline (3); colitis (3); coronary artery disease (3); heart failure (3); inflammation (3); Intellectual disability (3); metastatic tumors (3).
A further 162 diseases each share a sentence with ADAR in 3 papers or fewer.